ADIPOR2 (adiponectin receptor 2)
Description:
Receptor for ADIPOQ, an essential hormone secreted by adipocytes that regulates glucose and lipid metabolism. Required for normal body fat and glucose homeostasis. ADIPOQ-binding activates a signaling cascade that leads to increased PPARA activity, and ultimately to increased fatty acid oxidation and glucose uptake. Has intermediate affinity for globular and full-length adiponectin. Required for normal revascularization after chronic ischemia caused by severing of blood vessels (By similarity).
Synonyms: PAQR2; ACDCR2
Tractability: Small molecule: a structure with a bound ligand is known. Antibody: UniProt places it where antibodies can reach, with high confidence; its Gene Ontology location is reachable by antibodies, with high confidence; UniProt predicts a signal peptide or a membrane-spanning region. PROTAC: ubiquitination databases record sites on it; a small molecule that binds it is known.
Target class: Membrane receptor
Gene: Protein-coding gene on chromosome 12 (1,688,574 to 1,788,680, forward strand). Ensembl gene ENSG00000006831.
Subcellular location: Cell membrane
Pathways (Reactome):
Metabolism: AMPK inhibits chREBP transcriptional activation activity
Gene Ontology:
Molecular function: adipokinetic hormone receptor activity; adiponectin binding; protein binding; signaling receptor activity; identical protein binding
Biological process: adiponectin-activated signaling pathway; fatty acid oxidation; glucose homeostasis; hormone-mediated signaling pathway; positive regulation of cold-induced thermogenesis; vascular wound healing
Cellular component: plasma membrane; membrane
Genetic constraint (gnomAD): Loss-of-function variants: 17 observed, 40.09 expected, observed/expected ratio (o/e) 0.42, 90% interval 0.29 to 0.64. The upper end of that interval is the gene's LOEUF score, 0.64, which puts it in group 2 of 6, group 1 being the genes least tolerant of losing a copy. Missense variants: 276 observed, 489.37 expected, observed/expected ratio (o/e) 0.56, 90% interval 0.51 to 0.62. Synonymous variants: 160 observed, 170.45 expected, observed/expected ratio (o/e) 0.94, 90% interval 0.82 to 1.07.
Homologues: Orthologues: chimpanzee ADIPOR2 (100% identical), dog ADIPOR2 (96% identical), guinea pig ADIPOR2 (95% identical), pig ADIPOR2 (94% identical), rat Adipor2 (94% identical), mouse Adipor2 (93% identical), rabbit ADIPOR2 (89% identical), macaque ADIPOR2 (88% identical), tropical clawed frog adipor2 (82% identical), zebrafish adipor2 (71% identical). Paralogues in human: ADIPOR1 (67% identical), PAQR3 (25% identical), PAQR8 (19% identical), PAQR5 (19% identical), PAQR7 (18% identical), PAQR9 (18% identical), PAQR6 (17% identical), PAQR4 (15% identical), MMD2 (12% identical), MMD (11% identical).
Diseases named in the same sentence as ADIPOR2 in open-access papers:
ADIPOR2 is named in the same sentence as 119 diseases in open-access papers, as found by Europe PMC text mining. Sharing a sentence is not in itself a finding about the gene and the disease. The quoted sentences say what the papers report.
Insulin resistance (54 papers, 2006 to 2025). Increased resistance towards insulin, that is, diminished effectiveness of insulin in reducing blood glucose levels. "The role of the major adiponectin receptor gene, i.e., adiponectin receptor 2 (AdipoR2), has been linked to insulin resistance and type 2 diabetes, where it plays a crucial role in glucose and lipid metabolism, inflammation and oxidative stress." (PMID 36013366, 2022). "A consistent phenotype of insulin resistance was observed in AdipoR1 deficient mice, however studies in which AdipoR2 was deleted have reported opposing phenotypes in terms of glucose tolerance and susceptibility to diet-induced insulin resistance." (PMID 31920962, 2019). "A recent report showed that disruption of AdipoR1 and AdipoR2 in mice caused the mice to be more vulnerable to insulin resistance than adiponectin-knockout mice." (PMID 24490657, 2014). "For example, in adipocytes (WAT) from mice model, acute catecholamine administration is associated with development of insulin resistance due to reduced plasma levels of adiponectin and increased mRNA levels of receptors of adiponectin (adipoR2)." (PMID 24348550, 2013). "Associations between ADIPOR2 gene variants with insulin resistance and T2DM related phenotypes, triglyceride levels, liver fat content, and CAD have been reported in several human populations." (PMID 21943112, 2011). "Other genetic variations of ADIPOR2 have been associated with decreased triglyceride levels in Mexicans with insulin resistance and in Germans with metabolic syndrome." (PMID 20178558, 2010). "Single nucleotide polymorphisms (SNPs) of the ADIPOR2 have been associated with either insulin resistance or hepatic fat accumulation in various populations, albeit not in all studies." (PMID 20178558, 2010). "Various studies have associated genetic variants of the ADIPOR2 locus with insulin resistance and the traits of the metabolic syndrome, whilst several others have failed to confirm this." (PMID 20178558, 2010). "AdipoR2 was associated with the activation of peroxisome proliferator-activated receptor α pathways and the inhibition of inflammation and oxidative stress, which are involved in the induction of insulin resistance." (PMID 23922494, 2013). "Androgen treatment in preadipocytes could downregulate miR-375 expression and increase the level of adiponectin receptor 2 (ADIPOR2), which might help understand the mechanisms of how testosterone deficiency could lead to insulin resistance and visceral fat accumulation." (PMID 27703473, 2016). "A small molecule agonist (AdipoRon) that binds and activates signaling through both AdipoR1 and AdipoR2 improved insulin resistance and glucose intolerance and increased the lifespan of obese mice." (PMID 38979340, 2024). "Moreover, leptin-deficient mice presented increased AdipoR1 and AdipoR2 mRNA expression, indicating low circulating adiponectin levels and defective adiponectin signaling, which have been linked to glucose metabolism deregulation, insulin resistance and diabetes." (PMID 39201365, 2024). "Release of adiponectin by exercise stimulates AdipoR1 and AdipoR2 to reduce insulin resistance and mitigate metabolic syndrome." (PMID 37964253, 2023). "ATF3 can also transcriptionally repress adiponectin receptor-2 (AdipoR2) gene expression by directly binding to the 5′ flanking promoter region of AdipoR2 and thus interfere with the protective effect of adiponectin on obesity-related insulin resistance." (PMID 36472556, 2023). "ADIPO has a protective effect on liver dysfunction in obesity,T2DM,and other insulin resistance states, and ADIPOR2 is mainly expressed in liver." (PMID 34641739, 2021). "We previously showed that orally active AdipoR agonist AdipoRon ameliorated insulin resistance and glucose intolerance in mice fed a high-fat diet, which was completely obliterated in AdipoR1 and AdipoR2 DKO (mouse R1·R2DKO) mice." (PMID 33420419, 2021).
Insulin resistance (continued). "Recently, seven markers based on the BMI-sensitive pathway of insulin resistance, adipoR1, adipoR2, ObR, IRβ, IRS-1, IGF-1R, and IGF-2R, have been proposed to develop a new molecular typing system for endometrial cancer." (PMID 31440472, 2019). "Alteration in Adiponectin receptor 1 (ADIPOR1) and Adiponectin receptor 2 (ADIPOR1) ADIPOR2 is important for development of insulin resistance in NIDDM." (PMID 30678306, 2019). "Both AdipoR1-null and AdipoR2-null mice exhibited similar phenotypes with both strains showing increased adiposity and insulin resistance." (PMID 31920962, 2019). "Adiponectin is known to decrease hepatic insulin resistance and to attenuate liver inflammation and fibrosis through binding to AdipoR1 and AdipoR2, the latter is preferentially expressed in rodents livers." (PMID 29768504, 2018). "Obesity also decreases adiponectin sensitivity by downregulating the expression of AdipoR1 and AdipoR2 adiponectin receptors, which in turn leads to insulin resistance." (PMID 27881129, 2016). "Polymorphisms in adiponectin-related genes (ADIPOQ, ADIPOR1, ADIPOR2) have been examined for relationships with obesity, insulin resistance and diabetes, cardiovascular disease, and to circulating adipokine levels, but many gaps in knowledge remain." (PMID 24586568, 2014). "Increasing the expression levels of AdipoR1 and AdipoR2 in the liver of mouse models of obesity and type 2 diabetes can improve insulin resistance and diabetes." (PMID 24490657, 2014). "Similar evidences were extracted on adiponectin receptor (AdipoR) studies, as adipoR1 and adipoR2 knockout mice exhibit mild insulin resistance." (PMID 23762871, 2013). "Further, AdipoR2 knockout mice showed reduced diet-induced insulin resistance but promoted type 2 diabetes." (PMID 23762871, 2013). "In patients with chronic HCV, hepatic expression of AdipoR1, and AdipoR2 appeared to be differentially regulated in the setting of hepatic insulin resistance, as measured by hepatic PEPCK expression, and in response to serum adiponectin." (PMID 23914225, 2013). "Mice deficient for either or both receptors were glucose intolerant, and adenovirus mediated expression of AdipoR1 and AdipoR2 in liver improved obesity-related insulin resistance and T2DM in db/db mice through AMPK and PPARα pathways, respectively." (PMID 21943112, 2011). "Assuming a paracrine effect of adiponectin, the up-regulated adiponectin/AdipoR2 system in ScWAT in obese rats may represent a compensatory mechanism against insulin resistance and down-regulated AdipoR1 by obesity." (PMID 39576482, 2025). "Adipor1 and Adipor2 are known to be downregulated in obesity-related insulin resistance." (PMID 35804799, 2022). "Indeed, AdipoR1 and AdipoR2 were found to regulate insulin sensitivity in insulin target tissues, and are important in the pathophysiology of insulin resistance." (PMID 34395490, 2021). "Interestingly, AdipoR1 and AdipoR2 double-knockout mice have increased triglyceride levels and exhibit insulin resistance, demonstrating that AdipoR1 and AdipoR2 regulate lipid and glucose homeostasis." (PMID 34783654, 2021). "This suggests that both upregulation of AdipoR1 and AdipoR2 expression and agonism of AdipoRs could be potential targets for novel treatments for insulin resistance and type 2 diabetes." (PMID 30974901, 2019). "Simultaneous disruption of both AdipoR1 and AdipoR2 abolished adiponectin binding and actions, resulting in increased liver triglyceride content, inflammation and oxidative stress in adipose tissue, and consequent insulin resistance and glucose intolerance." (PMID 29107297, 2017). "ADIPOR2 expression is negatively correlated with obesity traits as it is speculated to have a protective role in insulin resistance, since expression increased when obese subjects undergo physical exercise." (PMID 26222688, 2015).
Insulin resistance (continued). "WR increased the gene expression of AdipoR2, which can accelerate fatty acid oxidation and glucose intake, and WR also decreased protein expressions of LCN2, which has been implicated in the development of obesity and insulin resistance." (PMID 23434909, 2013). "Assuming that adiponectin receptors AdipoR1 and AdipoR2 mediate the antidiabetic and antiinflammatory effects of adiponectin, we hypothesized that genetic variation in AdipoR1 and AdipoR2 may contribute to insulin resistance, dyslipidemia, and inflammation." (PMID 16700915, 2006). "The purpose of this study was to determine whether variations in the AdipoR1 and AdipoR2 genes may contribute to insulin resistance, dyslipidemia and inflammation." (PMID 16700915, 2006). "Adiponectin receptors have been detected in human monocytes and macrophages and recently it was found that variants of the AdipoR2 could be a determinant for atherosclerosis independent of insulin resistance." (PMID 21284833, 2011). "Our findings suggest that variants of ADIPOR2 could be a determinant for atherosclerosis independent of insulin resistance status, possibly by affecting ADIPOR2 protein levels." (PMID 20178558, 2010). "AdipoRon is an oral synthetic small molecular compound as it has a feasible effect on reducing insulin resistance and blood glucose tolerance in high-fat diet mice by specifically binding to APN receptors AdipoR1 and AdipoR2." (PMID 36632609, 2021). "In liver, the mRNA levels of ADIPOR2 were increased or decreased in NASH, and the mRNA levels of both receptors were increased in insulin resistance." (PMID 21943112, 2011). "As one of the insulin-sensitizing fatty factors, APN is secreted by fat cells to improve insulin resistance and attenuate hyperglycemia as well as impair RANKL-stimulated RAW264.7 cells through its receptors as AdipoR1, AdipoR2, and T-Cadherin and its downstream factors of cohesive protein APPL1." (PMID 36632609, 2021). "Along this view, the findings that adiponectin and ADIPOR2 were negatively correlated, respectively, with white blood cells and HOMA-IR would suggest the existence of a link among adiponectin signalling, low-grade inflammation, and insulin resistance." (PMID 24454366, 2013). "The aim of the present study was to evaluate the protective effect of concurrent exercise in the degree of the insulin resistance in mice fed with a high-fat diet, and assess adiponectin receptors (ADIPOR1 and ADIPOR2) and endosomal adaptor protein APPL1 in different tissues." (PMID 23046739, 2012). "In particular, mouse mutants lacking adiponectin, the ligand for AdipoR1 and AdipoR2, develop metabolic complications (glucose intolerance, insulin resistance) only when fed a high fat diet, which is analogous to the C. elegans paqr-2 mutants that show severe phenotypes when fed a SFA-rich diet." (PMID 28886012, 2017). "Moreover, the disruption of AdipoR1 and AdipoR2 almost completely abolished adiponectin binding in the liver, leading to an increase in triglyceride content, oxidative stress, and inflammation, which resulted in NAFLD and insulin resistance." (PMID 24490657, 2014). "Additionally, adiponectin signaling (AdipoR2, APPL1, and pAMPK/AMPK ratio) in the liver was found to be impaired in these animals, which could reduce fatty acid oxidation capacity, thereby increasing lipid accumulation and consequently exacerbating insulin resistance." (PMID 39339665, 2024).
Obesity (44 papers, 2010 to 2025). Accumulation of substantial excess body fat. "measured miRNAs in whole breast milk that target mRNA of leptin (LEP), adiponectin (ADIPOQ) and their respective receptors (LEPR, ADIPOR1 and ADIPOR2) which are associated with obesity." (PMID 33801634, 2021). "We also identified nominally significant associations between ADIPOR1 rs10920533 and total cholesterol and ADIPOR2 rs11061971 and obesity risk." (PMID 30816311, 2019). "The objective of this work was to analyze the expression of AdipoR1 and AdipoR2, modulated by differential concentrations of leptin in an obesity model (10 ng/mL, 100 ng/mL, and 1000 ng/mL) associated with breast cancer in MCF-7 and HCC1937 cell lines." (PMID 29311755, 2017). "Accordingly, ADIPOQ and ADIPOR2 expression in the skin appear negatively correlated with obesity in the same way as the serum ADIPOQ level." (PMID 34438765, 2021). "In a previous study, Adipor2 was inversely proportional to the degree of obesity and was identified as a potential therapeutic target for treating obesity." (PMID 34638602, 2021). "The evaluation performed evidenced that adiponectin and ADIPOR2 skin expression is negatively correlated with the serum adiponectin level and accordingly with obesity." (PMID 34438765, 2021). "AdipoR2−/− mice were resistant to obesity induced by a high‐fat diet and exhibited improved glucose tolerance and decreased plasma cholesterol levels (Fontana, Vinciguerra, & Longo, 2012)." (PMID 31625260, 2020). "In the present study, they demonstrate that over-expression of AdiopR1 and AdipoR2 improves whole body glucose metabolism and hepatic insulin sensitivity and opposes hepatic steatosis in obesity." (PMID 28271029, 2017). "Random glucose levels were unaffected by either overexpression of AdipoR1 and AdipoR2 or HFD-induced obesity." (PMID 28145500, 2017). "Collectively, these results identify overlapping effects of AdipoR1 and AdipoR2 as well as additional, distinct effects of the latter that provide a foundation for further investigations aimed at reducing obesity-related complications." (PMID 28145500, 2017). "In contrast, AdipoR2-/- mice were resistant to high-fat diet induced obesity and exhibited improved glucose tolerance and decreased plasma cholesterol levels." (PMID 24324556, 2013). "In muscle, the expression levels of ADIPOR1 and ADIPOR2 correlated positively with obesity, glucose and insulin levels and insulin resistance." (PMID 21943112, 2011). "In the current literature on the upstream activation proteins of AMPK and PPARα, it is well-established that adiponectin binds to adiponectin receptors AdipoR1 and AdipoR2 and exerts anti-lipid effects in obesity via activation of AMPK and PPARα pathways, respectively." (PMID 40176148, 2025). "Conversely, AdipoR2 protein content increased with obesity (p < 0.01)." (PMID 39576482, 2025). "Studies suggested that adiponectin could correlate with obesity and dementia as AdipoR1 and AdipoR2 suppression promotes neurodegeneration." (PMID 37363537, 2023). "Furthermore, the expression of the intra-abdominal adipose tissue-adiponectin receptor 2 (AdipoR2) is reduced in obesity and is inversely correlated with plasma levels of triglycerides." (PMID 36430774, 2022). "For example, overexpression of miR-126b-5p promoted obesity in mice by directly targeting Adipor2." (PMID 35682902, 2022). "Additionally, the adiponectin level and ADIPOR1/ADIPOR2 expression are reduced in obesity and obesity-related diseases and likely contribute to the characteristic low-grade inflammation because of the absence of the anti-inflammatory effects of adiponectin." (PMID 26147005, 2015). "Thus, the overexpression of AdipoR1 in the liver of a mouse model of human obesity caused an increase in the activation of the AMPK pathway, while the overexpression of AdipoR2 caused an increase in the expression of peroxisome proliferator activated receptor alpha (PPAR-α) target genes." (PMID 34860303, 2022).